PARP2 (poly(ADP-ribose) polymerase 2)
Description:
Poly-ADP-ribosyltransferase that mediates poly-ADP-ribosylation of proteins and plays a key role in DNA repair. Mediates glutamate, aspartate or serine ADP-ribosylation of proteins: the ADP-D-ribosyl group of NAD(+) is transferred to the acceptor carboxyl group of target residues and further ADP-ribosyl groups are transferred to the 2'-position of the terminal adenosine moiety, building up a polymer with an average chain length of 20-30 units. Serine ADP-ribosylation of proteins constitutes the primary form of ADP-ribosylation of proteins in response to DNA damage. Mediates glutamate and aspartate ADP-ribosylation of target proteins in absence of HPF1. Following interaction with HPF1, catalyzes serine ADP-ribosylation of target proteins; HPF1 conferring serine specificity by completing the PARP2 active site. PARP2 initiates the repair of double-strand DNA breaks: recognizes and binds DNA breaks within chromatin and recruits HPF1, licensing serine ADP-ribosylation of target proteins, such as histones, thereby promoting decompaction of chromatin and the recruitment of repair factors leading to the reparation of DNA strand breaks. HPF1 initiates serine ADP-ribosylation but restricts the polymerase activity of PARP2 in order to limit the length of poly-ADP-ribose chains. Specifically mediates formation of branched poly-ADP-ribosylation. Branched poly-ADP-ribose chains are specifically recognized by some factors, such as APLF. In addition to proteins, also able to ADP-ribosylate DNA: preferentially acts on 5'-terminal phosphates at DNA strand breaks termini in nicked duplex.
Synonyms: PARP-2; ARTD2; pADPRT-2; ADPRT2; ADPRTL2; ADPRTL3
Tractability: Small molecule: an approved drug acts on it; a structure with a bound ligand is known; a high-quality ligand is known; it has a binding pocket of medium quality; it belongs to a druggable protein family. PROTAC: it is named in the literature on targeted protein degradation; ubiquitination databases record sites on it; a small molecule that binds it is known.
Target class: Enzyme; Transferase
Chemical probes: (8R,9S)-Talazoparib, AZ0108 (high quality), E7449 (high quality), OLAPARIB (high quality), TALAZOPARIB (high quality), TALAZOPARIB, VELIPARIB (high quality), XAV939, niraparib (high quality)
Gene: Protein-coding gene on chromosome 14 (20,343,601 to 20,357,905, forward strand). Ensembl gene ENSG00000129484.
Subcellular location: Nucleus; Chromosome
Subcellular location (Human Protein Atlas): Nucleoplasm; Nucleoli
Pathways (Reactome):
DNA Repair: DNA Damage Recognition in GG-NER; Dual Incision in GG-NER; Formation of Incision Complex in GG-NER; HDR through MMEJ (alt-NHEJ); POLB-Dependent Long Patch Base Excision Repair
Gene Ontology:
Molecular function: chromatin binding; damaged DNA binding; NAD DNA ADP-ribosyltransferase activity; NAD+ poly-ADP-ribosyltransferase activity; NAD+-protein mono-ADP-ribosyltransferase activity; NAD+-protein-aspartate ADP-ribosyltransferase activity; NAD+-protein-glutamate ADP-ribosyltransferase activity; NAD+-protein-serine ADP-ribosyltransferase activity; nucleosome binding; poly-ADP-D-ribose binding; poly-ADP-D-ribose modification-dependent protein binding; protein binding
Biological process: DNA ADP-ribosylation; DNA damage response; DNA repair; DNA repair-dependent chromatin remodeling; protein auto-ADP-ribosylation; protein poly-ADP-ribosylation; decidualization
Cellular component: chromosome; nucleolus; nucleoplasm; nucleus; site of DNA damage
Genetic constraint (gnomAD): Loss-of-function variants: 39 observed, 49.11 expected, observed/expected ratio (o/e) 0.79, 90% interval 0.61 to 1.04. The upper end of that interval is the gene's LOEUF score, 1.04, which puts it in group 4 of 6, group 1 being the genes least tolerant of losing a copy. Missense variants: 498 observed, 552.72 expected, observed/expected ratio (o/e) 0.9, 90% interval 0.84 to 0.97. Synonymous variants: 164 observed, 195.82 expected, observed/expected ratio (o/e) 0.84, 90% interval 0.74 to 0.95.
Homologues: Orthologues: chimpanzee PARP2 (100% identical), macaque PARP2 (98% identical), dog PARP2 (88% identical), rabbit PARP2 (88% identical), pig PARP2 (87% identical), mouse Parp2 (85% identical), guinea pig PARP2 (84% identical), rat Parp2 (84% identical), tropical clawed frog parp2 (61% identical), zebrafish parp2 (60% identical), Caenorhabditis elegans parp-2 (26% identical). Paralogues in human: PARP1 (40% identical), PARP3 (33% identical).
Diseases named in the same sentence as PARP2 in open-access papers:
PARP2 is named in the same sentence as 76 diseases in open-access papers, as found by Europe PMC text mining. Sharing a sentence is not in itself a finding about the gene and the disease. The quoted sentences say what the papers report.
breast cancer (32 papers, 2010 to 2026). A primary or metastatic malignant neoplasm involving the breast. "In the mouse mammary tumor virus–polyoma middle T antigen (MMTV–PyMT) mouse model of spontaneous breast cancer, PARP2 deficiency in the entire mouse or the breast delayed tumor onset, without affecting the growth rate." (PMID 40904702, 2025). "In another syngeneic breast cancer model, the proficient AT‐3 breast cancer cell line was implanted into WT mice and those with T cell‐specific PARP2 deficiency." (PMID 40904702, 2025). "Discoveries in genetic etiology have been important for the development of novel treatments in other cancers, such as PARP-2 inhibitors in breast cancer patients carrying mutations in the BRCA1 gene." (PMID 23236348, 2012). "Conversely, in another syngeneic mouse model of bone metastasis‐prone breast cancer, PARP2 deficiency increased bone metastasis by altering the balance between regulatory T and T helper 1 cells, thereby converting the bone microenvironment into an immunosuppressive state." (PMID 40904702, 2025). "PARP2 mutations have been associated with breast cancer risk, but similarly to PrCa, their functional impact remains unclear." (PMID 39001544, 2024). "In model mice with a single deficiency in T cell PARP1 or PARP2, there is no change in the number of T cells in peripheral lymphoid tissues, but the double deficiency of PARP1 and PARP2 leads to a reduction in peripheral CD4+ CD8+ T cells in breast cancer model mice." (PMID 38111536, 2023). "In addition, compared to mice with a single deficiency in PARP1, a single deficiency in PARP2, or normal control mice, breast cancer mice with PARP1/2 double deficiencies have a higher percentage of CD11b+DCs in cancer tissues." (PMID 38111536, 2023). "By establishing innovative experiment tools combining in vitro and in vivo, gain- and loss-of-function, genetic and pharmacological approaches, this study has identified and characterized PARP2 deficiency as a mediator of breast cancer bone metastasis that functions via multiple mechanisms." (PMID 32221289, 2020). "Our data suggest for the first time that a SNP in PARP2, rs878156, may together with other genetic variants modulate cancer specific survival in breast cancer patients depending on chemotherapy." (PMID 26674097, 2015). "Compared with control mice, AT‐3‐induced tumor growth was significantly reduced in host mice, indicating the crucial role of PARP2 in regulating T cell responses in breast cancer." (PMID 40904702, 2025). "Compared to mice with single deficiencies in T cell PARP1 or PARP2, mice with PARP1/2 double deficiencies have faster proliferating breast cancer cells and reduced CD4+ and CD8+ T cell infiltration in tumor tissues." (PMID 38111536, 2023). "Olaparib is a United States Food and Drug Administration (FDA)-approved dual inhibitor of poly [ADP-ribose] polymerase 1 (PARP-1) and PARP-2 for the treatment of advanced ovarian and breast cancers." (PMID 38260135, 2023). "Herein, new prototypes of PARP-2 inhibitors were designed aiming to develop antitumor therapeutics to treat breast cancer." (PMID 36171229, 2022). "Of these twenty, three showed evidence of association with LoF variants for overall breast cancer (ZFAND1, TYRO3, TMEM206/PACC1), and a further six with breast cancer subtypes (DNAH11, PARP2, LAMC3, MTMR11, EPN3, SLC22A10)." (PMID 35884425, 2022). "PARP1 and PARP2 play critical roles in regulating DNA repair and PARP inhibitors have been approved for the treatment of BRCA1/2-mutated ovarian and breast cancers." (PMID 32029902, 2020). "We showed for the first time that the intronic rs878156 SNP in the BER gene PARP2 can modulate cancer specific survival in breast cancer patients depending on chemotherapy." (PMID 26674097, 2015). "A similar effect modification by PARP2 rs878156 was observed for breast cancer specific mortality after anthracycline-based chemotherapy." (PMID 26674097, 2015).
breast cancer (continued). "Of particular note, in breast cancer, inhibition of poly ADP-ribose polymerase 2 (PARP2) increases the risk of bone metastasis, as this leads to an increase in immature myeloid cells in the bone marrow, which inhibits Th cell recruitment and creates an immunosuppressive microenvironment." (PMID 38464516, 2024). "Collectively, it could be concluded that compounds 12 and 27 are promising anti-breast cancer agents that act as PARP-2 inhibitors with potent apoptotic activity." (PMID 36171229, 2022). "We found nominal evidence of association with breast cancer overall for LoF variants in three genes (ZFAND1, TMEM206/PACC1, and TYRO3), with ER-negative breast cancer in two genes, DNAH11 and PARP2, and with ER-positive disease in four genes LAMC3, MTMR11, EPN3, and SLC22A10." (PMID 35884425, 2022). "Besides, the inhibitor target PARP2 also been verified effective to treat cancer such as breast cancer, ovarian cancer, hepatocellular carcinoma, cervical cancer." (PMID 33486472, 2021). "Olaparib is a PARP1 and PARP2 dual inhibitor recently FDA approved for advanced breast cancer treatment; its effects on bone metastasis are unknown." (PMID 32443642, 2020). "Since olaparib, a potent PARP-1, PARP-2 and PARP-3 inhibitor, has shown remarkable efficacy in BRCA mutated breast cancer 65, 66, a phase I/II trial tested the combination of 300 mg of olaparib twice daily and eribulin (at standard dose and schedule) in TN advanced BC patients." (PMID 31762800, 2019). "The bioinformatics study revealed a correlation between PARP2 and BRCA1/2 and ERBB2 in the basal subgroup of breast cancer patients." (PMID 40141415, 2025). "There was also a correlation between PARP2 and BRCA1/2 and ESR1 in the HER2 subgroup of breast cancer patients." (PMID 40141415, 2025). "It was also shown that there was a correlation between PARP2 and BRCA1/2 in the luminal B subgroup, indicating that those breast cancer patients can receive Anti-HER2 Monoclonal Antibodies as therapeutic drugs available in the clinic at present." (PMID 40141415, 2025). "We also demonstrate that, as in breast cancer, OTI-611 traps CHD1L, PARP1, and PARP2 onto chromatin." (PMID 39684869, 2024). "The ELISA assay showed that YHP-836 dose-dependently reduced intracellular PAR levels in MX-1 breast cancer cells, which reflected the catalytic activity of PARP1 and PARP2." (PMID 35910366, 2022). "Through immunofluorescence, PARP-2 was obviously expressed in the nucleus of human ovarian cancer Hela cells, human breast cancer MCF-7 cells, and human osteosarcoma U-2 OS cells, which indicated that PARP-2 expression is low cell line specificity." (PMID 35466317, 2022). "A study reported that Olaparib induced breast cancer-mediated bone metastasis via PARP-2, but not PARP-1, in the myeloid lineage, not in the tumor cells." (PMID 38260135, 2023). "This is inconsistent with a recent study that showed that olaparib increased breast cancer bone metastasis via PARP2 but not PARP1 using myeloid cells." (PMID 35269669, 2022). "Here we show that olaparib increases breast cancer bone metastasis through PARP2, but not PARP1, specifically in the myeloid lineage, but not in the cancer cells." (PMID 32221289, 2020). "A new study shows that Olaparib might increase breast cancer bone metastasis through PARP2 (poly ADP-ribose polymerase), but not PARP1, particularly in myeloid lineage and not in cancer cells." (PMID 32443642, 2020).
ovarian carcinoma (19 papers, 2012 to 2025). A malignant neoplasm originating from the surface ovarian epithelium. "Olaparib is the first PARP1 and PARP2 inhibitor approved for treatment of refractory ovarian cancer harboring BRCA1 or BRCA2 mutation." (PMID 31554189, 2019). "A series of new therapeutic agents that are potent inhibitors of the PARP1 and PARP2 isoforms have demonstrated important clinical activity in patients with breast or ovarian cancers that are caused by mutations in either the BRCA1 or 2 genes." (PMID 22401667, 2012). "Comparatively, the BRCA1 mutated UWB1.289 cancer cells demonstrated a much lower PARP1 and a reduced PARP2 mRNA transcription than the other ovarian cancer cell lines tested (t-test, p < 0.001)." (PMID 34440232, 2021). "To validate the GSEA results, we then detected the expression of cell cycle (PCNA and PLK1), DNA replication (MCM2 and MCM3) and BER pathways-related proteins (PARP1 and PARP2) in ovarian cancer cells transiently overexpressed ARHGAP10." (PMID 27010858, 2016). "Patients with BRCA mutations have improved overall response to platinum-based therapy, which is associated with longer survival in patients with BRCA-mutated ovarian cancer.PARP enzymes, especially PARP-1 and PARP-2, play a key role in the repair of DNA single-strand breaks." (PMID 38952544, 2024). "Rucaparib is a potent PARP-1 and PARP-2 oral inhibitor, which is approved by FDA in December 2016 and by EMA in May 2018 as monotherapy for the treatment of advanced BRCA-mutated ovarian cancer, relapsed after at least two chemotherapy lines." (PMID 31109041, 2019). "Specially, the drug Niraparib could target to the PARP2 in this community and it was one of the most familiar drug for recurrent ovarian cancer." (PMID 31068972, 2019). "The aim of this report was to assess the potential antitumor effects of three novel B-lactam-steroid alkylating compounds on human ovarian cancer cells, together with their potential to inhibit PARP1/PARP2 activity." (PMID 34440232, 2021). "PARP1 and PARP2 dual inhibitors, such as olaparib, have been recently FDA approved for the treatment of advanced breast and ovarian cancers." (PMID 32221289, 2020). "Olaparib is the first inhibitor of the PARP enzymes 1, 2, and 3 (PARP-1, PARP-2, and PARP-3 respectively) developed in ovarian cancer." (PMID 31109041, 2019). "In order to repair the generated genotoxicity and DNA damage induced by the lactam steroidal alkylators ASA-A and ASA-B, the cells of all the examined human ovarian cancer cell lines responded with significantly elevated transcription levels of PARP1 and PARP2 mRNA." (PMID 34440232, 2021).
anemia (14 papers, 2020 to 2025). A reduction in the number of red blood cells, the amount of hemoglobin, and/or the volume of packed red blood cells. "The exact mechanism of PARPis causing anaemia is not fully understood, and one explanation is that PARP-2 inhibition leads to inhibition of erythropoiesis." (PMID 39885555, 2025). "A deficiency in PARP2 significantly disrupts the differentiation of erythroid lineage cells in mice, resulting in heightened hemolytic reactions and subsequent anemia." (PMID 39695097, 2024). "In addition to PARP-1, a critical role in developing hematologic adverse events, particularly anemia, is attributed to PARP-2, as its inhibition has been linked to chronic anemia in animal models." (PMID 40804462, 2025). "Concurrently, the inhibition of PARP2 has been implicated to be responsible for certain hematological side effects observed with current clinical PARP inhibitors, such as anemia." (PMID 39695097, 2024). "A previous study showed that inhibition of PARP-2 affected the differentiation of erythroid cells and reduced the lifespan of red blood cells, leading to red blood cell reduction and anemia." (PMID 35401230, 2022). "A previous study reported that erythropoietin production is increased in a compensatory manner in PARP-2-/- mice and contributes to the maintenance of erythropoiesis, thus suggesting that erythropoietin may have an effect on ameliorating the risk of severe anemia." (PMID 36267984, 2022). "Consequently, inhibiting PARP-2 can lead to significant toxicities, including anemia and neutrophil count fluctuations." (PMID 39712485, 2024). "It has been suggested that the PARP-2 protein might be involved in erythropoiesis, so its inhibition may be responsible for the anemia AE." (PMID 37835597, 2023). "Anemia may be a one of the targeted AEs related to PARP2 inhibition and erythropoiesis." (PMID 32622363, 2020). "Nonclinical study results have shown that PARP2 plays an essential role in erythropoiesis, suggesting that anaemia is related to PARP2 inhibition." (PMID 34795408, 2022). "Indeed, in PARP-2 deficient mouse models, PARP-2 inhibition was shown to impair the differentiation of erythroid progenitors and shorten the lifespan of erythrocytes, suggesting that exogenous supplementation may not be the most effective means of managing anemia." (PMID 40804462, 2025).
prostate carcinoma (7 papers, 2019 to 2024). A carcinoma that arises from epithelial cells of the prostate gland. "PARP-2 expression has also been associated with prostate cancer progression." (PMID 39201718, 2024). "Selective targeting of PARP-2 inhibited AR-positive prostate cancer cell growth and tumor growth in vivo." (PMID 39201718, 2024). "Studies have shown higher expressions of PARP1 and PARP2 in prostate cancer compared with benign tissues, and PARP2 expression correlates with biochemical recurrence." (PMID 37686423, 2023). "Following recent additional approvals, PARP1/PARP2 inhibitors are currently used against breast, ovarian, pancreatic, and prostate cancers." (PMID 34210965, 2021). "Olaparib is inhibiting PARP1, PARP2, and PARP3 and is used as a therapy for cancer in people with hereditary BRCA1 or BRCA2 mutations, which include some ovarian, breast and prostate cancers." (PMID 33481867, 2021). "Other recent studies support a relevant role of PARP-1/PARP-2 in prostate cancer biology, not only related to the well-described functions in DNA damage repair, but also as regularors of transcription factors." (PMID 31366128, 2019). "A transcriptional role for MYCN in upregulating the DDR has been given further credence by the recent identification of MYCN binding sites in the promoters of PARP1, PARP2, BRCA1, RMI2, and TOPBP1, albeit in castration resistant prostate cancer." (PMID 32577161, 2020). "Selective targeting of PARP-2 by genetic or pharmacological approaches blocks the interaction between PARP-2 and FOXA1, attenuating AR-mediated gene expression and inhibiting AR-positive prostate cancer growth." (PMID 31366128, 2019).
cervical cancer (5 papers, 2014 to 2021). A primary or metastatic malignant neoplasm involving the cervix. "MiR-383 suppresses cervical cancer cell proliferation, invasion and metastasis by inhibiting PI3K/Akt pathway via the downregulating of PARP2." (PMID 31340767, 2019). "Chromatid scattering was observed in cervical cancer cells with increased PARP1 and PARP2 protein levels (HeLa, C33-A), suggesting that PARP1 and PARP2 protein levels could be used as a predictive biomarker for the efficiency of olaparib treatment, as previously proposed." (PMID 29262611, 2017).